EAPP (E2F associated phosphoprotein)
Description:
May play an important role in the fine-tuning of both major E2F1 activities, the regulation of the cell-cycle and the induction of apoptosis. Promotes S-phase entry, and inhibits p14(ARP) expression.
Synonyms: C14orf11; BM036; FLJ20578
Tractability: PROTAC: ubiquitination databases record sites on it.
Gene: Protein-coding gene on chromosome 14 (34,515,938 to 34,539,721, reverse strand). Ensembl gene ENSG00000129518.
Subcellular location: Cytoplasm; Nucleus
Subcellular location (Human Protein Atlas): Nucleoplasm; Nuclear speckles
Gene Ontology:
Molecular function: protein binding
Biological process: negative regulation of transcription elongation by RNA polymerase II; positive regulation of cell population proliferation; positive regulation of transcription elongation by RNA polymerase II
Cellular component: nuclear speck; nucleoplasm; nucleus; cytoplasm
Genetic constraint (gnomAD): Loss-of-function variants: 28 observed, 26.64 expected, observed/expected ratio (o/e) 1.05, 90% interval 0.78 to 1.44. The upper end of that interval is the gene's LOEUF score, 1.44, which puts it in group 5 of 6, group 1 being the genes least tolerant of losing a copy. Missense variants: 307 observed, 323.02 expected, observed/expected ratio (o/e) 0.95, 90% interval 0.87 to 1.04. Synonymous variants: 102 observed, 112.24 expected, observed/expected ratio (o/e) 0.91, 90% interval 0.77 to 1.07.
Homologues: Orthologues: chimpanzee EAPP (99% identical), macaque EAPP (98% identical), pig EAPP (92% identical), dog EAPP (90% identical), rat Eapp (87% identical), mouse Eapp (87% identical), rabbit EAPP (84% identical), tropical clawed frog eapp (64% identical), zebrafish eapp (61% identical), Caenorhabditis elegans F48E8.2 (34% identical).
Diseases named in the same sentence as EAPP in open-access papers:
EAPP is named in the same sentence as 6 diseases in open-access papers, as found by Europe PMC text mining. Sharing a sentence is not in itself a finding about the gene and the disease. The quoted sentences say what the papers report.
endothelial dysfunction (1 paper, 2021). In vascular diseases, endothelial dysfunction is a systemic pathological state of the endothelium (the inner lining of blood vessels) and can be broadly defined as an imbalance between vasodilating and vasoconstricting substances produced by (or acting on) the endothelium. "Most notably, endothelial dysfunction (impairment of endothelium-dependent relaxations) induced by aging was significantly exacerbated in aged eAPP−/− mice aortas as compared to age-matched WT mice." (PMID 34382945, 2021).
renal cell carcinoma (1 paper, 2018). "In renal cell carcinoma cell lines miR-145-5p is dysregulated and several targets, including e2F-associated phosphoprotein (EAPP), Heparan Sulfate 6-O-Sulfotransferase 2 (HS6ST2), Lysyl Oxidase (LOX), Transforming Growth Factor beta-2 (TGFB2) and Vaccinia-related Kinase 2 (VRK2), were confirmed." (PMID 30102719, 2018).
ZIKV infection (1 paper, 2017). "Further examination of the roles of metabolic control genes such as TERT, ALDH7A1, CREB5, EAPP, and NDUFA11 as they relate to ZIKV infection may provide further insights into ZIKV pathogenesis." (PMID 28442752, 2017).
tumor (2 papers, 2022 to 2025). "BRAF downregulation links to EAPP mutants affecting tumor growth and patient outcomes." (PMID 41009348, 2025). "Cluster 1 was characterized by upregulation of tumor-suppressing genes: HNF1B, CCNDBP1, PATJ, EPB41L3, MARVELD2, PTEN in conjunction with cell-cycle genes – GSPT1, GPR19, EAPP, KIT, CDKL1, and stem cell markers – RBBP5, NANOG, NCSTN, ERG, including quiescent stem cell markers—FOXP1, SMARCA2." (PMID 36348001, 2022).
EAPP also shares sentences with these, for which no sentence is quoted: Azoospermia (1 paper); prostate carcinoma (1).